POLD4 (DNA polymerase delta 4, accessory subunit)
Description:
As a component of the tetrameric DNA polymerase delta complex (Pol-delta4), plays a role in high fidelity genome replication and repair. Within this complex, increases the rate of DNA synthesis and decreases fidelity by regulating POLD1 polymerase and proofreading 3' to 5' exonuclease activity. Pol-delta4 participates in Okazaki fragment processing, through both the short flap pathway, as well as a nick translation system. Under conditions of DNA replication stress, required for the repair of broken replication forks through break-induced replication (BIR), a mechanism that may induce segmental genomic duplications of up to 200 kb. Involved in Pol-delta4 translesion synthesis (TLS) of templates carrying O6-methylguanine or abasic sites. Its degradation in response to DNA damage is required for the inhibition of fork progression and cell survival.
Synonyms: POLDS; p12
Tractability: Small molecule: an approved drug acts on it; a structure with a bound ligand is known. PROTAC: UniProt records ubiquitination sites on it; ubiquitination databases record sites on it; its protein half-life has been measured.
Gene: Protein-coding gene on chromosome 11 (67,350,772 to 67,356,972, reverse strand). Ensembl gene ENSG00000175482.
Subcellular location: Nucleus
Subcellular location (Human Protein Atlas): Centriolar satellite
Pathways (Reactome):
DNA Repair: Dual Incision in GG-NER; Dual incision in TC-NER; Gap-filling DNA repair synthesis and ligation in GG-NER; Gap-filling DNA repair synthesis and ligation in TC-NER; HDR through Homologous Recombination (HRR); PCNA-Dependent Long Patch Base Excision Repair; Recognition of DNA damage by PCNA-containing replication complex; Termination of translesion DNA synthesis
Cell Cycle: Polymerase switching on the C-strand of the telomere; Processive synthesis on the C-strand of the telomere; Removal of the Flap Intermediate from the C-strand; Telomere C-strand (Lagging Strand) Synthesis
DNA Replication: Polymerase switching; Processive synthesis on the lagging strand; Removal of the Flap Intermediate
Gene Ontology:
Molecular function: protein binding; DNA-directed DNA polymerase activity
Biological process: DNA-templated DNA replication; DNA synthesis involved in DNA repair; DNA replication
Cellular component: delta DNA polymerase complex; nucleus; nucleoplasm
Genetic constraint (gnomAD): Loss-of-function variants: 8 observed, 11.35 expected, observed/expected ratio (o/e) 0.7, 90% interval 0.41 to 1.27. The upper end of that interval is the gene's LOEUF score, 1.27, which puts it in group 5 of 6, group 1 being the genes least tolerant of losing a copy. Missense variants: 121 observed, 118.1 expected, observed/expected ratio (o/e) 1.02, 90% interval 0.88 to 1.19. Synonymous variants: 61 observed, 52.23 expected, observed/expected ratio (o/e) 1.17, 90% interval 0.95 to 1.45.
Homologues: Orthologues: chimpanzee POLD4 (100% identical), macaque POLD4 (98% identical), dog POLD4 (92% identical), guinea pig POLD4 (91% identical), pig POLD4 (84% identical), mouse Pold4 (83% identical), rat Pold4 (83% identical), zebrafish pold4 (42% identical).
Diseases named in the same sentence as POLD4 in open-access papers:
POLD4 is named in the same sentence as 18 diseases in open-access papers, as found by Europe PMC text mining. Sharing a sentence is not in itself a finding about the gene and the disease. The quoted sentences say what the papers report.
lung carcinoma (8 papers, 2015 to 2025). "The loss of POLD4 in human lung cancer cells leads to genomic instability, suggesting a novel function for POLD4 in controlling Polδ’s response to DNA damage." (PMID 41083899, 2025). "Low expression of POLD4 was reported to weaken the DNA repair systems including nucleotide excision repair and increase the risk of lung cancer formation." (PMID 32855967, 2020). "Reduced expression of the POLD4 gene has been associated with lung cancer and a poor prognosis for certain lung cancer patients." (PMID 28737709, 2017). "The reduced expression of POLD4 encoding p12 protein has been found in lung cancer, which induces genomic instability." (PMID 26460955, 2015). "Research has indicated that a significant tobacco carcinogen, the benzopyrene analogue 4NQO, downregulated the expression level of the POLD4 gene, resulting in a decreased nucleotide excision repair and further leading to genomic instability, ultimately elevating the risk of lung cancer formation." (PMID 37762224, 2023). "POLD4 (rank 8) has been associated with genomic instability in lung cancer." (PMID 25569148, 2015). "The inhibition of POLD4 in lung cancer cells was discovered to impede the progression of the G1-S cell cycle transition, thereby causing heightened genomic instability." (PMID 37762224, 2023). "Huang and colleagues discovered that reducing POLD4 levels in lung cancer cells not only delays the progression via the G1-S cell cycle transition but also results in heightened genomic instability." (PMID 37762224, 2023). "POLD4 has an important role in genomic instability, double-stranded DNA breaks (DSBs) and lung cancer." (PMID 35941578, 2022). "Currently, research on POLD4 in cancer is primarily focused on lung cancer." (PMID 37762224, 2023). "Therefore, the role of POLD4 showed tissue specificity in gastric cancer and lung cancer." (PMID 32855967, 2020). "For example, an RS signature including genes involved in DNA polymerases (POLA1, POLD4, POLE4) was found to be predictive for ATRi response in lung cancer preclinical models." (PMID 38555285, 2024). "Additionally, evidence indicates that POLD4 may serve as a promising novel target for lung carcinoma, given its selective impact on cancer cells without affecting normal cells." (PMID 37762224, 2023).
glioma (3 papers, 2020 to 2024). A benign or malignant brain and spinal cord tumor that arises from glial cells (astrocytes, oligodendrocytes, ependymal cells). "Secondly, while we conducted experimental validation, we admit that the exact molecular mechanisms underlying POLD4’s role in glioma cell proliferation and the modulation of the immune microenvironment remain incompletely understood." (PMID 37762224, 2023). "POLD4 influences the proliferation of glioma cells and is associated with various immune cells in gliomas, with the strongest correlation observed with macrophages." (PMID 37762224, 2023). "Moreover, the study unearthed noteworthy associations between deviant POLD4 expression and an array of factors, encompassing the tumor microenvironment, efficacy of immunotherapy, drug sensitivity, and glioma cell proliferation." (PMID 37762224, 2023). "Our analysis results indicate a significant correlation between POLD4 expression and the WHO grade, 1p19q deletion status, age, and IDH mutation status of gliomas." (PMID 37762224, 2023). "Using experimental analysis, we further confirmed the overexpression of POLD4 in gliomas, as well as its correlation with glioma recurrence, proliferation, and the suppressive immune microenvironment." (PMID 37762224, 2023). "Taken together, these outcomes serve to reinforce the significant impact of POLD4 on the clinical characteristics and survival outcomes of glioma patients." (PMID 37762224, 2023). "As expected, the high-POLD4 group showed significantly higher expression of PCNA, CD163, CD206, and PDL1 compared to the low-POLD4 group, further confirming the correlation between POLD4 and glioma cell proliferation and the immunosuppressive microenvironment." (PMID 37762224, 2023). "To summarize, the elevated expression of POLD4 serves as an indicator of malignant characteristics in tumors such as gliomas, suggesting an unfavorable prognosis and contributing to the formation of an immunosuppressive microenvironment within the tumor." (PMID 37762224, 2023). "Based on the results of bioinformatic analysis, we proceeded to validate the expression of POLD4 in glioma tissues and cell lines." (PMID 37762224, 2023). "By conducting knockdown experiments targeting POLD4 in glioma cell lines U251 and U87, we have unraveled compelling evidence underscoring the pivotal role of POLD4 in governing the proliferation of glioma cells." (PMID 37762224, 2023). "The knockdown of POLD4 exerts a profound effect on cell viability, and the clonogenic potential of glioma cells is markedly reduced upon POLD4 inhibition." (PMID 37762224, 2023). "To further verify our findings, we employed immunohistochemistry to visualize POLD4 expression in adjacent normal brain tissue, primary glioma, and recurrent glioma." (PMID 37762224, 2023). "To further validate the significance of POLD4 in gliomas, we performed validation on other datasets of gliomas, including CGGA-mRNAseq_325, CGGA-mRNAseq_693, CGGA-mRNA_array_301, and Rembrandt cohorts." (PMID 37762224, 2023). "According to the expression levels of POLD4, we divided 20 cases of glioma into the low-POLD4 group and the high-POLD4 group." (PMID 37762224, 2023). "This research on tissue specimens further supports the role of POLD4 in glioma cell proliferation and its impact on the glioma immune microenvironment." (PMID 37762224, 2023). "We found that, compared to normal astrocyte cell lines, POLD4 was expressed at higher levels in various glioma cell lines." (PMID 37762224, 2023). "Twenty glioma tissue specimens were collected, and based on POLD4 expression, they were divided into the low POLD4 expression group and the high POLD4 expression group." (PMID 37762224, 2023). "To assess the potential of POLD4 as a prognostic indicator for patient response to immunotherapy, we first evaluated the correlation between the expression level of POLD4 in gliomas and the efficacy of immunotherapy using the TIDE algorithm." (PMID 37762224, 2023).
glioma (continued). "To analyze the oncogenic roles of POLD4 in gliomas, we conducted an analysis of the expression of POLD4 and its correlation with other genes in both GBM and LGG cases." (PMID 37762224, 2023). "In this section, we focus on analyzing the relationship between POLD4 gene expression and clinical features of gliomas, as well as the impact of POLD4 gene expression on glioma survival." (PMID 37762224, 2023). "Remarkably, POLD4 showed significant overexpression in multiple glioma cell lines, particularly in U87." (PMID 37762224, 2023). "Through qPCR, we established that POLD4 is markedly upregulated in glioma tissues compared to the adjacent normal brain tissues." (PMID 37762224, 2023). "We collected tumor tissue samples from 20 glioma patients and performed immunohistochemical staining for POLD4, PCNA, CD163, CD206, and PDL1." (PMID 37762224, 2023). "Based on these research findings, we attempted to explore the impact of POLD4 on glioma proliferation and the immune microenvironment in glioma tissues using immunohistochemical experiments." (PMID 37762224, 2023). "Finally, we conducted a study on the correlation of POLD4 expression with cell proliferation markers PCNA, tumor-associated macrophage markers (CD163, CD206), and the immune checkpoint PDL1 in glioma tissue." (PMID 37762224, 2023). "Additionally, we examined the differences in survival among glioma patients with high and low expression levels of POLD4." (PMID 37762224, 2023). "POLD4 exerts a significant impact on the survival of gliomas, including both LGG and GBM." (PMID 37762224, 2023). "POLD4 plays a crucial role in DNA replication, and we speculate that this may be a significant mechanism through which POLD4 influences the proliferation of glioma cells." (PMID 37762224, 2023). "This substantial increase in expression suggests that POLD4 may not only be involved in glioma tumor growth but also play a role in the glioma recurrence process." (PMID 37762224, 2023). "Our findings suggest that POLD4 could serve as a potential prognostic biomarker for glioma patients." (PMID 37762224, 2023). "Furthermore, compared to normal brain tissues adjacent to the tumor, POLD4 expression was significantly elevated in glioma tissues, particularly in recurrent gliomas." (PMID 37762224, 2023). "Specifically, higher-grade gliomas tend to have higher POLD4 expression." (PMID 37762224, 2023). "Therefore, in subsequent research, we placed particular emphasis on investigating the effects of POLD4 on gliomas." (PMID 37762224, 2023). "We conducted a thorough investigation to validate the expression of POLD4 in gliomas." (PMID 37762224, 2023). "Therefore, we analyzed the expression of PCNA in the low-POLD4 group and the high-POLD4 group to assess the impact of POLD4 on glioma proliferation." (PMID 37762224, 2023). "This suggests that POLD4 may play a role in age-related glioma development and in a subset of gliomas with IDH alterations." (PMID 37762224, 2023). "To further explore the potential of POLD4 in glioma, we conducted further analysis on the expression levels of POLD4 in glioma patients with different clinical characteristics using the CGGA_mRNAseq_325, CGGA_mRNAseq_693, CGGA_array_301, and Rembrandt datasets." (PMID 37762224, 2023). "EDU uptake experiments confirmed that POLD4 knockdown could reduce EDU incorporation in glioma cells, indicating that POLD4 can inhibit glioma cell proliferation." (PMID 37762224, 2023). "Notably, glioma tissues displayed higher POLD4 expression, especially in recurrent cases." (PMID 37762224, 2023). "CCK-8 experiments indicated that POLD4 knockdown could suppress the viability of glioma cells." (PMID 37762224, 2023). "We found that compared to the low POLD4 expression group, the high POLD4 expression group exhibited higher levels of PCNA, CD163, CD206, and PDL1 expression in glioma tissue." (PMID 37762224, 2023).
glioma (continued). "Additionally, we analyzed the correlation between POLD4 and the markers of tumor-associated macrophages, CD163 and CD206, as well as the expression of the immune checkpoint PDL1 to explore the effect of POLD4 on the immunosuppressive microenvironment in gliomas." (PMID 37762224, 2023). "Furthermore, the EDU incorporation assay found that POLD4 knockdown led to a significant reduction in EDU uptake, corroborating its role as a player in the regulation of glioma cell proliferation." (PMID 37762224, 2023). "Besides POLD4, HOXB2 was also demonstrated to be a direct target of miR-1200 and mediated the tumor-suppressing role in human osteosarcoma and glioma cells." (PMID 32855967, 2020). "However, our data showing higher POLD4 expression in patients without the codeletion implies that POLD4 might contribute to a more aggressive glioma phenotype in these cases." (PMID 37762224, 2023).
gastric cancer (2 papers, 2020 to 2022). A primary or metastatic malignant neoplasm involving the stomach. "miR-1200/POLD4 pathway mediated the promoting role of circ_0026359 in CDDP resistance of gastric cancer." (PMID 32855967, 2020). "For the downstream pathway, POLD4 was examined to be a direct target of miR-1200 in CDDP-resistant gastric cancer cells." (PMID 32855967, 2020). "Rescue experiments had examined that miR-1200/POLD4 mediated the role of circ_0026359 in CDDP resistance of gastric cancer cells." (PMID 32855967, 2020). "The miR-1200/POLD4 pathway might mediate the role of circ_0026359 in CDDP resistance of gastric cancer cells." (PMID 32855967, 2020). "Low expression levels of POLD4 might decrease the genomic stability of CDDP-resistant gastric cancer cells and consequently decrease cell viability and cell colony formation, increase caspase-3/7 activity and DNA fragmentation, and therefore decrease CDDP resistance in gastric cancer cells." (PMID 32855967, 2020). "Therefore, POLD4 was a direct target of miR-1200 in CDDP-resistant gastric cancer cells." (PMID 32855967, 2020). "Therefore, miR-1200 mediated the promoting role of circ_0026359 in CDDP resistance of gastric cancer cells, and the miR-1200/POLD4 and miR-1200/HOXB2 pathways might be the downstream mechanisms involved in CDDP resistance of gastric cancer." (PMID 32855967, 2020). "In the present study, we demonstrated that depletion of circ_0026359 enhanced the activities of miR-1200 and consequently decreased the expression level of POLD4, and the CDDP resistance of gastric cancer cells decreased." (PMID 32855967, 2020). "miR-1200/POLD4 pathway was regulated by circ_0026359 and mediated the role of circ_0026359 in CDDP resistance of gastric cancer." (PMID 32855967, 2020). "In addition, POLD4 was identified to be a direct target of miR-1200 and was negatively regulated by miR-1200 in CDDP-resistant gastric cancer cells." (PMID 32855967, 2020).
medulloblastoma (2 papers, 2023). A malignant, invasive embryonal neoplasm arising from the cerebellum. "For example, almost all the genes in the mismatch repair pathway have elevated gene expression levels in medulloblastoma, except EXO1, RPA3 and POLD4." (PMID 36918656, 2023).
autism spectrum disorder (1 paper, 2024). A spectrum of developmental disorders that includes autism, and Asperger syndrome. "For example, ZFP57 is associated with autism spectrum disorder and PTSD symptoms, while POLD4 is linked to schizophrenia." (PMID 39020437, 2024).
esophageal adenocarcinoma (1 paper, 2023). A malignant tumor with glandular differentiation arising predominantly from Barrett mucosa in the lower third of the esophagus. "The use of cBioPortal to analyze genetic alterations in POLD4 demonstrated that the gene exhibited the highest alteration frequency (>6%) in patients diagnosed with esophageal adenocarcinoma." (PMID 37762224, 2023).
melanoma (1 paper, 2024). A malignant, usually aggressive tumor composed of atypical, neoplastic melanocytes. "Further integrative analysis revealed that patients harboring SBS7a had significantly elevated expression of DNA damage repair-related proteins, such as PRKDC, ATR, and POLD4, suggesting that elevated DNA damage repair contributes to poor prognosis in patients with melanoma." (PMID 39039072, 2024).
prostate carcinoma (1 paper, 2026). A carcinoma that arises from epithelial cells of the prostate gland. "In conclusion, this study has identified POLD4 as a potent target for radiosensitization, capable of disrupting DNA damage-repair homeostasis through MRI-monitored gene editing, thereby offering a promising strategy to enhance the efficacy of radiotherapy in prostate cancer." (PMID 41498761, 2026). "In this study, transcriptomic analysis of radiotherapy-treated prostate cancer cells revealed a marked upregulation of DNA polymerase delta subunit 4 (POLD4), a target that has not been systematically studied." (PMID 41498761, 2026).
schizophrenia (1 paper, 2024). A major psychotic disorder characterized by abnormalities in the perception or expression of reality. "For instance, altered methylation of RIPOR2 was associated with trauma exposure, and POLD4 is linked to schizophrenia risk." (PMID 39020437, 2024).
Sepsis (1 paper, 2022). Sepsis is defined as life-threatening organ dysfunction caused by a dysregulated host response to infection. "The genomic instability caused by POLD4 may exacerbate the prognosis of sepsis patients." (PMID 35265105, 2022). "Meanwhile, the present study identified eight metabolism-related genes (NME1, NME6, POLD4, POLE4, POLR2J, POLR2L, ADCY3, and ENTPD1) in patients with sepsis and the identified metabolism-related genes may represent diagnostic and therapeutic biomarkers of sepsis." (PMID 35265105, 2022).